IFNG (interferon gamma)
Diseases named in the same sentence as IFNG in open-access papers (continued):
Sharing a sentence is not in itself a finding about the gene and the disease.
pneumonia (170 papers, 2009 to 2025). An acute, acute and chronic, or chronic inflammation focally or diffusely affecting the lung parenchyma, caused by an infection in one or both of the lungs (by bacteria, viruses, fungi, or mycoplasma.). "Based on these findings it is obvious that IFNγ is crucial to control and confine pneumonia caused by C. pneumoniae." (PMID 22096480, 2011). "Using TLR2/4 double-deficient mice we show that TLR2 and TLR4 regulate IFNγ-secretion in vivo during pneumonia caused by C. pneumoniae." (PMID 22096480, 2011). "Failure of IFNγ to induce NO in TLR2/4 double-deficient cells represents one possible mechanism why TLR2/4 double-deficient mice are unable to control pneumonia caused by C. pneumoniae and succumb to the infection." (PMID 22096480, 2011). "Upon challenge with C. pneumoniae MyD88-deficient mice succumbed like TLR2/4-deficient mice to progressive pneumonia, although pulmonary IFNγ-levels were increased like in wild type mice six days post infection." (PMID 22096480, 2011). "Significant differences between genotypes that exceeded 1.5-fold in male mice with S. pneumoniae pneumonia include higher concentrations of IFNγ, IL-12 (p40), IL-17A and MCP-1 (CCL2) in HRB-Mertk-/- compared to wild type males." (PMID 40238852, 2025). "Such a correlation between decreased IFNγ, IL6 levels and spleen atrophy has previously been reported in an experimental stroke model, where increased mortality caused by pneumonia was noted." (PMID 37259163, 2023). "To establish that MyD88 are required for S. pneumoniae induced lung IFNγ, we adoptively transferred (i.n.)WT, STING−/−, or MyD88−/− monocytes to CCR2−/− mice and examined the IFNγ production in the lung by S. pneumonia." (PMID 34512626, 2021). "Nevertheless, EVs isolated from IFNγ pre-activated human umbilical cord-derived MSCs were shown to increase the survival of rats with Escherichia coli-induced pneumonia and to reduce the lung injury." (PMID 34685707, 2021). "In patients with S. pneumoniae sepsis, plasma IFNγ was elevated and correlated with increased mortality." (PMID 34512626, 2021). "We examined S. pneumonia-induced lung IFNγ production in CD11ccreSTINGfl/fl and LysMcreSTINGfl/fl mice." (PMID 34512626, 2021). "In vitro and in vivo data show that during P. aeruginosa induced pneumonia, Exo T increases interferon gamma (IFN-γ) production by natural killer (NK) cells in lungs." (PMID 32252376, 2020). "Zinc supplementation showed benefits, shortening the duration of oxygen desaturation, tachypnea, and clinical symptoms in children with pneumonia, showing a Th1 response with the increase of IFNγ and IL-2 cytokines." (PMID 31803694, 2019). "S. pneumonia-infected Dectin-2KO mice had a shorter survival time, larger bacterial burden and lower interferon gamma (IFN-γ) production in the lungs than WT mice." (PMID 26727976, 2016). "In comparison with control mice, animals that received recombinant HMGB1 showed fivefold higher bacilli loads, the double of pneumonia and significant lower expression of IFNγ, TNFα and IL-17, while the expression of IL-10 was significantly higher." (PMID 26201072, 2015). "Increased concentrations of SLPI can be found in infection, for example, in pneumonia, whereas downregulation is triggered by interferon-gamma (IFN-γ)." (PMID 26185365, 2015). "Mice that lack the antiviral cytokine IFNγ or the IFNγ receptor exhibit increased susceptibility to MHV68 infection, characterized by uncontrolled lytic infection, pathology-induced pneumonia, fibrosis of the lungs and spleen, and death." (PMID 24587276, 2014). "This is accompanied by an increased frequency of CD4+IFNγ+ effector T-cells which cannot prevent lethal pneumonia." (PMID 22096480, 2011). "Vaccination of MyD88-deficient mice with M. bovis BCG induced IFNγ-producing CD4+ T-cells in vivo, but the TH1 cells only partially prevented lethal pneumonia upon challenge with M. tuberculosis." (PMID 22096480, 2011).
pneumonia (continued). "Both viral miRNAs and the TMER4-derived ncRNA are important for latency establishment in wild-type (WT) mice and do not elicit lethal pneumonia observed following WT MHV68 infection in IFNγ-deficient mice (13, –, 15)." (PMID 40444975, 2025). "Treated animals showed a significantly higher percentage of lymphocytes positive to IFNγ around blood vessels and airways, as well as in the airway epithelium, while TNFα immunostained macrophages were significantly more numerous in areas of pneumonia." (PMID 36671276, 2022). "Statistical assessment of patients with acute myeloid leukemia (AML) and myelodysplastic syndromes (MDS) treated with ICIs revealed enrichment of IFNγ+ IL-17- CD8+ T and CXCR3+ CCR6+ Th17/Th1 cells in BALF in the group developing pneumonia." (PMID 38426102, 2024). "In addition, molecular signatures of cell-mediated immunity, such as IL12p40, IFNG, and GZMB, in the M5 group were specifically and significantly higher than those in the NC, M4, and severe groups, suggesting their protective and pathogenic roles in moderate pneumonia." (PMID 36776879, 2023). "Seven hub genes, IL4, IL6, CSF2, IFNG, IL1B, TNF and IL17A, were responsible for Experimental Lung Inflammation, Pneumonitis, Pneumonia and Lobar Pneumonia." (PMID 36989283, 2023). "Similar to the antibody responses we observed, there were higher numbers of S. aureus-specific IL-17A and IFNγ-secreting T cells following SSTI, compared with pneumonia, at 4 weeks post-infection." (PMID 35983063, 2022). "Differential expression of IL-17 in BAL IFNγ+ IL-17- CD8+ T and CXCR3+ CCR6+ Th17/Th1 cells was noted in BAL fluid of patients with ICI-Pneumonitis compared to patients with pneumonia; however, larger studies are needed to confirm these findings." (PMID 34675810, 2021). "Interferon gamma (IFN-γ), an important cytokine in the host defense against infection, which is derived mainly from NK and CD4+ T cells during pneumonia." (PMID 31447768, 2019). "In fact, these viruses markedly induced the expressions of pro-inflammatory cytokines and chemokines including IL6, IL1α, IL1β, TNFα, IFNγ and CCL5 in the lungs, resulting in severe pneumonia." (PMID 21826229, 2011). "By contrast, mice exposed to concentrated ambient particles and interferon gamma, had increased BAL neutrophils and more severe pneumonia at 24 h." (PMID 20958976, 2010). "respiratory disease dataset, we observed significant enrichment of IFNγ signatures in cystic fibrosis and COVID‐19 infection, IL‐33 in COPD and COVID‐19, IL‐4 + IL‐13 in pneumonia, and TGFβ signatures in pulmonary fibrosis (PF) and chronic rhinosinusitis (CRS)." (PMID 40926620, 2025). "In contrast, pneumonia did not result in increased accumulation of IL-17A and IFNγ-producing T cells specific for Hla, LukE, or LukS-PV in the spleen." (PMID 35983063, 2022). "Indeed, persistent pneumonia and SSTI elicited strong toxin-specific antibody and CD4+ IL-17+ and IFNγ+ T cell responses, whereas transient pneumonia did not." (PMID 41050694, 2025). "Principal changes were a) increase of absolute monocyte counts; b) selective defect of TNFα and IFNγ production from PBMCs after stimulation with S.pneumoniae; and c) increase of absolute counts of Tregs mainly observed among patients with H1N1-related pneumonia." (PMID 20037642, 2009). "In comparison with the control group, animals that received blocking HMGB1 antibodies after 60 days of infection showed a significant increase of pulmonary bacilli burdens, lower expression of IFNγ, TNFα and IL17, high expression of IL-10, and higher but not significant pneumonia (39+/3% vs 32+/3%)." (PMID 26201072, 2015).
pancreatic cancer (164 papers, 2003 to 2025). "Another study showed that anti-PD-L1 VHH fused with two cytokines IL2 and IFNγ overcame the delivery barrier caused by an immunosuppressive tumor microenvironment and dense stroma surrounding tumors in an orthotropic pancreatic tumor model." (PMID 37746282, 2023). "Type II IFN (IFNγ) treatment can cause cell cycle arrest and inhibit the growth of pancreatic cancer cells by triggering caspase-1- and IRF1-dependent apoptosis." (PMID 35140750, 2022). "Splenic proteins associated with muscle and body weight preservation in the pancreatic cancer PDX mice (IFNγ, IL-17A) were produced at higher levels in the less cachectic PDX group and splenic IL-8, associated with body weight loss, was produced at higher levels in the more cachectic PDX group." (PMID 30513792, 2018). "Recent studies have shown a beneficial effect of IFNγ on the response of pancreatic cancer to immunotherapies, supporting our findings." (PMID 40917508, 2025). "In pancreatic cancer for example, loss of SMAD4 impairs T-cell infiltration and chemokine production, leading to a poorly immunogenic tumor microenvironment with reduced IFNγ-driven PD-L1 expression." (PMID 41155227, 2025). "IFNγ suppresses peritoneal ductal adenocarcinoma (PDAC) in the rat orthotopic pancreatic cancer model." (PMID 40862157, 2025). "Functionally, the H-1PV and IFNγ combination augments the macrophage and splenocyte production against pancreatic cancer cells." (PMID 40862157, 2025). "In pancreatic cancer, the expression level of interferon gamma (IFN-γ)-related genes was closely related to the patient’s prognosis." (PMID 41384105, 2025). "Despite pancreatic tumor, the release of IFNγ by NK‐cells was crucial for the successful treatment of the B16 melanoma tumor model." (PMID 38109851, 2024). "Subsequently, CD8+ T cells perform their anti‐tumor benefits by recognizing the pancreatic tumor‐cell antigen and producing IFNγ within the TME." (PMID 38109851, 2024). "We showed that VISTA significantly reduces the TNFα and IFNγ expression of CD4+ or CD8+ T cells cocultured with pancreatic tumor cells." (PMID 37190254, 2023). "While CD107a and IFNγ expression were elevated in MV-BiKE cocultures of patient-derived pancreatic cancer cultures, increased BiKE-mediated bystander killing was only observed in cocultures of the more MV-sensitive culture." (PMID 36765035, 2023). "As shown, in Setd2KO tumor‐bearing mice, blockade of Ly6G had a similar effect as a‐PD‐1 on reducing pancreatic tumor burden and increasing IFNγ production in tumor‐infiltrating CD8+ T cells." (PMID 36453584, 2023). "Although it has been assumed that caspase-1 does not cause apoptosis, recent reports have suggested that, in human pancreatic cancer cells, caspase-1 plays an important role in cell death by inducing interferon gamma." (PMID 35719997, 2022). "In a mouse model of pancreatic cancer, IFNγ expression by splenocytes after IRE and PD-L1 expression by tumor cells after IFNγ treatment has been demonstrated." (PMID 35372046, 2022). "STAT1 is activated by interferon-γ (IFNγ) in pancreatic stellate cells (PSCs), which plays an important role in chronic pancreatitis and pancreatic cancer." (PMID 33505218, 2021). "In pancreatic cancer, IFNγ increases the expression of PD-L1 and induces EMT through the STAT1 signaling pathway, which promotes immunosuppression and metastasis." (PMID 33406733, 2021). "Taken together, these results indicated that the IFNγ/STAT1 pathway suppressed FOXM1 transcription directly in pancreatic cancer cells." (PMID 30782607, 2019). "Fortunately, IFNγ can sensitize pancreatic cancer cells to gemcitabine via the STAT1/FOXM1/NFκB axis." (PMID 30782607, 2019). "Taken together, these results suggest that IFNγ increases the sensitivity of pancreatic cancer to gemcitabine." (PMID 30782607, 2019).
pancreatic cancer (continued). "Akin to our previous observation, patients with brain tumor mounted a significantly lower IFNγ response to EBNA-1 as well as CMV-pp65 compared to patients with pancreatic cancer (p < 0.001)." (PMID 29970101, 2018). "Regarding the response to viral antigens EBNA-1 and CMV-pp65, patients with brain tumor [GBM, OA/OD, astrocytoma (A) and brain metastasis (M)] produced significantly less IFNγ as compared to patients with pancreatic cancer as well as HD (p < 0.001)." (PMID 29970101, 2018). "The response to the positive control (PHA) showed a significant lower IFNγ production by patients with brain tumor compared to patients with pancreatic cancer as well as HD (p < 0.001)." (PMID 29970101, 2018). "The present report describes for the first time CMV- and EBV-specific immune responses—characterized by antigen-specific IFNγ production and humoral immune responses—in chemotherapy-naïve patients with pancreatic cancer or brain tumor." (PMID 29970101, 2018). "Here we show that mesothelin-specific interferon gamma (IFN-γ) production by peripheral blood lymphocytes is a reliable predictor of survival among patients with pancreatic cancer." (PMID 29854291, 2018). "In the pancreatic cancer study, we also found IFNG expression as being correlated with PDL1 expression, as reported by others." (PMID 27589570, 2016). "Accordingly, pancreatic stellate cells were found to be more sensitive to IFNγ-mediated growth inhibition than pancreatic cancer cells." (PMID 23284277, 2012). "The case study, presented here, investigates interferon-gamma (IFNγ) induced STAT1 signalling in two cell types that play a key role in pancreatic cancer development: pancreatic stellate and cancer cells." (PMID 23284277, 2012). "Using in vivo and in vitro models of pancreatic cancer, we have now studied IFNγ effects on the tumor cells themselves." (PMID 21310022, 2011). "Here, we have analyzed the biological and molecular effects of IFNγ in rat pancreatic cancer cells, using a combined experimental and computational approach." (PMID 21310022, 2011). "In a heterotopic nude mouse model of pancreatic cancer, IFNγ significantly inhibited the growth of tumors containing co-transplanted stellate cells, which accelerated tumor progression." (PMID 21310022, 2011). "PSC are more sensitive to the antiproliferative action of IFNγ than DSL-6A/C1 pancreatic cancer cells." (PMID 21310022, 2011). "In addition, it was found that CDK1/2/5/9 inhibition overcomes IFNγ-mediated adaptive immune resistance in pancreatic cancer." (PMID 40264756, 2025). "Moreover, depletion of NT5E, ATG5, FOXP3, and IFNG inhibited the colony formation ability of pancreatic cancer cell." (PMID 38395786, 2024). "Since upregulation of IFN-γ production is one of the key mechanisms in tumor regression, we monitored the levels of IFN-γ levels in PDAC tumors by double-labeling tumor tissues with IFNγ and CA19-9, a commonly used PDAC diagnostic marker used to detect pancreatic cancer treatment." (PMID 38136341, 2023). "However, after the deletion of GPR116 receptor, the proportion of NK cells in pancreatic cancer increased significantly, and the expression level of GzmB and IFNγ in NK cells were also increased." (PMID 36895027, 2023). "In an animal model of orthotopic pancreatic cancer, gut microbiome eradication by antibiotics reduced subcutaneous tumor growth and liver metastases, which was related to a significant increase in interferon gamma-producing T cells and a decrease in IL-17A and IL-10 producing T cells." (PMID 34884327, 2021). "Furthermore, CALR was significantly correlated with key immunity‐killing molecules, including PRF1, GZMB, and IFNG in pancreatic cancer." (PMID 32508042, 2020). "Furthermore, peritumoral injection of recombinant IFNγ or IL-17A inhibited colon and pancreas tumor growth compared to controls." (PMID 33042110, 2020).
pancreatic cancer (continued). "Therefore, blocking STAT1/FOXM1/NFkB axis by interferon γ (IFNγ) can increase the sensitivity of pancreatic cancer to gemcitabine." (PMID 30782607, 2019). "We acknowledge that this study is limited the investigation to the anti-viral immune response characterized by the CMV-specific IgG level and the IFNγ production by circulating immune cells in blood in patients with brain cancer in comparison with those with pancreatic cancer." (PMID 29970101, 2018). "Among the incriminated actors, some (IFNG, IL10, MDSC...) are directly implicated in and might explain the upregulation of PDL1 in pancreatic cancer." (PMID 27589570, 2016). "In pancreatic cancer, MDSCs are known to be induced by pro-inflammatory cytokines such as interleukins, granulocyte-macrophage colony-stimulating factor (GM-CSF), interferon gamma (IFN-γ), and tumor necrosis factor (TNF)." (PMID 27322081, 2016). "It has to be noted that the antitumor efficiency of IFNγ may also depend on the differentiation status of the pancreatic cancer cells: IFNγ-responsive DSL-6A/C1 tumors are relatively well differentiated." (PMID 21310022, 2011). "Remarkably, a similar trend was observed in a mouse model of orthotopic pancreatic cancer, where Sin3B loss significantly augmented CD8+ T cell infiltration, alongside heightened cytotoxicity against tumor cells, as evidenced by the upregulation of IFNγ and GzmB." (PMID 39316363, 2024). "However, high PD1 expression leads to CD8 + T cell exhaustion, and an increase in PD1 + CD8 + T cells and a decrease in TNFα + /IFNγ + CD8 + T cells due to ABHD17C in the pancreatic cancer microenvironment can promote the immune escape of tumor cells and inhibit immune killing." (PMID 37273016, 2023). "Akin to the findings in the pancreatic cancer trial that was conducted with the same adenoviral vector, in this study involving recurrent prostate cancer we observed similar trends in cytokine concentrations i.e., increase in serum IL-12, IFNγ and CXCL10 with increased adenoviral doses." (PMID 37713401, 2023). "Hence, while SMAD4 may have a modest inhibitory effect on PD-L1 in tumor cells, SMAD4 indirectly promotes PD-L1 expression in the pancreatic tumor microenvironment by enhancing T-cell infiltration and IFNγ biosynthesis." (PMID 35155243, 2022). "In addition, IFNγ is a promising agent to improve the effect of chemotherapy of pancreatic cancer." (PMID 30782607, 2019). "In pancreatic cancer, CDK1 inhibition has been shown to overcome IFNG-mediated adaptive immune resistance." (PMID 40746552, 2025). "This study found a strong link between interferon-gamma (IFN-γ) secretion from immune cells and changes in bone quality in pancreatic tumor-bearing humanized-BLT (hu-BLT) mice." (PMID 40940758, 2025). "In a murine model of pancreatic cancer, IRE treatment increased IFNγ expression compared to the sham control procedure." (PMID 35372046, 2022). "In the context of pancreatic tumors treated with IRE, the IFNγ–JAK–STAT1–ISG pathway, immune functions of ISGs, and feedback inhibition of this pathway pose some key questions to be answered." (PMID 35372046, 2022). "Using in vitro and in vivo pancreatic cancer models, we show that IDO1 expression is highly context dependent, influenced by attachment-independent growth and the canonical activator IFNγ." (PMID 33831358, 2021). "In summary, patients with brain tumor are more likely to mount lower IFNγ responses in whole blood to both EBNA-1 and CMV-pp65 compared to healthy individuals and patients with pancreatic cancer." (PMID 29970101, 2018). "Patients with brain tumor exhibited a significantly lower interferon gamma (IFNγ) response to EBNA-1 and CMV-pp65 compared to patients with pancreatic cancer or healthy donors." (PMID 29970101, 2018). "In addition, this gut microbiome can influence the serum level of IFN-γ and IL-2 and the pancreatic tumor immune infiltrates by increasing in numbers of CD8+ T cells, as well as activated T cells (CD8+/IFNγ+ T cells)." (PMID 40641916, 2025).